BCL2 (BCL2 apoptosis regulator)
Diseases named in the same sentence as BCL2 in open-access papers (continued):
Sharing a sentence is not in itself a finding about the gene and the disease.
cancer (continued). "However, It has been reported that the ratio of Bax to Bcl-2, rather than Bcl-2 alone, is important for survival of drug-induced apoptosis in cancer cells." (PMID 23874836, 2013). "By revealing Bcl-2 downregulation as the basic mechanism of action of PMC-A to promote apoptosis, this study also provides supporting evidence for justification of clinical trials based on antisense/SMI strategies directed against Bcl-2 protein in various cancers." (PMID 23441183, 2013). "However, the molecular mechanisms rendering cancer cells but not normal cells particularly sensitive to disrupting IP3R/Bcl-2 complexes are poorly understood." (PMID 23681227, 2013). "Indeed, cancers arising due to defects in BCL-2 were the first cancers shown to arise due to defective cell death, rather than due to defective cell duplication." (PMID 23840208, 2013). "Numerous anti-cancer strategies based on BH3 peptides derived from BH3-only proteins, anti-sense oligonucleotide or RNA interference targeting anti-apoptotic Bcl-2 family proteins, and non-peptidic small molecules binding specifically to anti-apoptotic Bcl-2 proteins have been developed." (PMID 23705845, 2013). "One of the integral hallmarks of cancer is cancer cell survival, and curcumin is able to block this via a number of molecules with a clear involvement in survival mechanisms, several of which are NF-κB dependent such as cFLIP, BCL-xL, BCL-2, XIAP, CIAP1, CIAP2, and surviving." (PMID 24278738, 2012). "Thus, the anti-cancer activities of Icariside II can be exerted by its pleiotropic effects on the multiple targets including STAT3 as well as JAK2, Src, and anti-apoptotic bcl-2, bcl-xL, survivin and COX-2 in U937 cells." (PMID 22493659, 2012). "Thus, inhibitors of these anti-apoptotic proteins, such as the Bcl-2 inhibitor ABT-737, may act synergistically with the MiTMAB dynamin inhibitors, broadening their therapeutic potential for the treatment of cancer." (PMID 21708043, 2011). "So, whether KLT induces apoptosis of cancer cell by down-regulating the expression of bcl-2 genes isn't yet clear, and its role in hepatoma is not learned, which requires further study and research." (PMID 18718024, 2008). "Cancer cells were characterised by low or absent Fas and Bcl-2 and high Bax expression." (PMID 12610520, 2003). "Furthermore, when we add methylation to the models of BCL2, the added variance of miRNA was increased by >25% in LUAD and ESCA, suggesting that the role of miRNA may be conditional on cis-methylation in these cancers." (PMID 40041206, 2025). "The activation of the Bax and Bcl-2 genes could not prevent the death of cancer cells." (PMID 41226774, 2025). "Compounds MJ2, MJ8, MJ15, and MJ19 had a stronger effect on the expression of the BCL2, MDM2, AIFM2, IL6, and IL8 genes in the healthy BEAS-2B cell line than in the cancerous HCT116 cell line, which may indicate their potential protective effect on normal cells with limited effect on cancer cells." (PMID 40725171, 2025). "The approval and use of the BCL-2:BIM complex-disrupting Venetoclax has heightened interest in finding precision medicine tools that could measure priming and, in doing this, identify cancer cells dependencies as vulnerabilities that could be addressed with therapy." (PMID 40507334, 2025). "Additionally, heat-shock protein 90 (HSP90) and BCL-2 inhibitors (e.g. XL888 and Obatoclax) were selected alongside cardiac glycosides (such as Lanatoside C, Proscillaridin A), inhibiting the Na+/K + ATPase pump, which represent an emerging therapeutic target in cancer." (PMID 41035005, 2025). "The stable expression of Bcl-2 in cells treated with extracts from E. echinus flowers could suggest that this anti-apoptotic protein has not been directly affected by the ongoing anti-cancer treatment." (PMID 38987732, 2024).
cancer (continued). "Notably, after knocking down STAT6 in macrophages, the expression of CD206 stimulated by IL-4 was not reduced by 23-HBA, and 23-HBA failed to inhibit the activation of the IL-10/STAT3/Bcl-2 signaling pathway induced by M2 macrophages and the resulting resistance to 5-FU in cancer cells." (PMID 38554148, 2024). "Because KIT and BCL2 are often highly expressed in POU2F3-positive tuft cell-like carcinomas, the same feature in WTs could suggest that non-neoplastic POU2F3-positive cells might express BCL2 and KIT via non-mutational, possibly epigenetic mechanisms that, in turn, might be smoking-related." (PMID 38358561, 2024). "In addition, AKT may be connected with cancer proliferation and apoptosis in epithelial ovarian tumour cells, possibly because of the involvement of AKT in the regulation of downstream signalling molecules, including CyclinD1, Bcl2, PCNA and MMP9." (PMID 37056382, 2023). "Indeed, the anti-apoptotic BCL-2 and BCL-XL are frequently expressed at high levels in a variety of cancers, and also in NCI-H460 and A549, which may contribute to chemoresistance of cancer cells." (PMID 35745782, 2022). "Similarly, in a recent report, the binding effect of flavonoids with BCL-2 i-motif was investigated where luteolin and quercetin was found to interact with BCL-2 i-motif with great affinity, giving the insight to understand the inhibitory condition of human cancer at the molecular level." (PMID 36134025, 2022). "Thus, it is not surprising that cancer cells dampen these damaging signals by overexpressing Bcl-2." (PMID 33466812, 2021). "Therefore, blocking the antiapoptotic and poor prognostic marker BCL2 and inducing the exogenous expression of the pro-apoptotic and favorable prognostic marker BAX in cancer tissues, could be considered in the development of antioncogenic therapies strategies." (PMID 34946681, 2021). "Hence, SI might have an anti-cancer effect by regulating BAD, caspase-9, Bcl-2, and eNOS." (PMID 34248628, 2021). "In addition, overexpression of miR-140-5p could inhibit proliferation, migration, and invasion and promote apoptosis in cancer by downregulating MAPK1, TRIM28, and YES1, further regulating levels of cleaved caspase-3, Bcl-2, and Bax, and blocking nuclear transport and Wnt/β-catenin signaling." (PMID 34479600, 2021). "Importantly, upregulation of certain anti-apoptotic BCL-2 family members, such as BCL-2, B cell lymphoma-extra-large (BCL-XL), and myeloid cell leukemia (MCL-1), are also known to support development and survival of cancerous cells as well as evasion from cancer therapy." (PMID 31937836, 2020). "Furthermore, we have selected few significant markers, such as survivin, Bcl-2, and MMP-9, for RT-PCR analysis that may represent important hallmarks of cancer, and the appearance of survivin, Bcl-2, and MMP-9 genes were substantially repressed upon FCN exposure." (PMID 31466313, 2019). "However, little information is currently available whether selective inhibition of BCL2 or other anti-apoptotic BCL-2 protein such as BCL(X)L also influences mitochondrial function and energetics in cancer cells, and whether these functions can be exploited therapeutically." (PMID 29899841, 2018). "The present study suggest that BaP can reverse the effects of drugs on cancer cells, including apoptosis, and this may be mediated by the activation of survival pathways such as MEK-ERK and Akt pathways in addition to upregulation of proteins such as Bcl-2 and Bcl-xL." (PMID 29673198, 2018).
cancer (continued). "Furthermore, chemotherapy or chronic BCL-2 inhibition in tumors initially sensitive to venetoclax may also lead to compensatory upregulation of MCL-1 and consequent emergence of drug-refractory cancer cells." (PMID 29269870, 2017). "Given various studies demonstrating that TRAIL therapy may be synergistic with Bcl-2 inhibitors and SMAC mimetics, we believe that there is a clear rationale for further investigation into combination therapies with TRAIL-Trimer to further potentiate apoptosis in cancer cells." (PMID 28827692, 2017). "In addition to the inflammation pathway, several cancer-related pathways were identified from the global NSAIDs-regulating miRNA-gene subnetwork, including cell cycle (CDK6, CCND1, CCKN1A, and E2F1), proliferation (MYC), apoptosis (BCL2) and angiogenesis (VEGFA)." (PMID 27329603, 2016). "As high levels of Bcl-2 may indicate that downstream apoptotic pathways are still functional and can be a marker of chemosensitivity and favorable prognosis in certain cancers, it is not surprising BCL2 abnormality did not have a prognostic role for MCL in this study." (PMID 26517511, 2015). "Furthermore, the translational relevance of these findings was assessed from the standpoint of generating a signature based on the expression and/or activation status of Rac1, Bcl-2 and STAT3, which could have implications for stratifying cancers by disease severity and chemoresistance." (PMID 26430964, 2015). "Furthermore, we demonstrate here that Bcl-2 expression is important in morin-induced apoptosis since cells overexpressing Bcl-2 were resistant to morin therapy, suggesting that morin may not exhibit anti-cancer effects in Bcl-2-overexpressing cells." (PMID 25561222, 2014). "In spite of the notion that Bcl-2 may represent a prototype for a new class of oncogenes and overexpression of Bcl-2 is common in many types of human cancer, no tumors were seen in our study, perhaps reflecting the fact that the Bcl-2 overexpression did not completely prevent apoptosis in the host." (PMID 23324128, 2013). "Indeed it is noteworthy that HME-1 mitochondria have neither Bim, nor Bcl-2 and only low level of Bcl-xL, which might distinguish them from sensitive cancer cell mitochondria." (PMID 20360986, 2010). "Moreover, BCL-2 expression was selectively enhanced in immune but not cancer cells." (PMID 17222352, 2007). "Thus, cancer cells may increase expression of Bcl-XL rather than Bcl-2 to be resistant to ligand-mediated cytotoxic stimuli including TRAIL." (PMID 12644829, 2003). "Evidently, ca. 80% cell death of the cancer cells, containing overexpressed LAT1 and downregulated Bcl‐2 protein, was observed, while normal 293T cells lacking the LAT1 receptor were almost unaffected." (PMID 40420627, 2025). "However, if cancer cells are MCL-1 primed, to a greater or lesser degree, then the patients harboring those “primed to adapt” cancer cells might be steered to a treatment that could target the MCL-1:BIM complexes cells even before relapse from BCL-2:BIM targeting treatment." (PMID 40507334, 2025). "Compared to cancer cell lines and HSPC, the expression of BCL2 is much lower in healthy MSC, explaining their lack of alterations after VEN exposure." (PMID 39531065, 2025). "Combining chemotherapy with the silencing of BCL-xL significantly increased cancer cell death from less than 20% to 60–70%, while silencing MCL-1 or BCL-2 had no substantial impact on sensitivity to chemotherapy." (PMID 38898061, 2024). "In our study, LP did not significantly modify the BAX/Bcl-2 ratio, nor the cleaved PARP expression level in HaCaT cells, thus revealing a selective activity on cancer cells." (PMID 38258008, 2024).
cancer (continued). "However, cancer cells relying on BCL2 and lacking MCL1/BCL2L1 might also be more resistant to CGs." (PMID 37904054, 2024). "At this juncture, it was observed that both the total level of BCL2 and the BCL2-BAX CPXs were not detectable in healthy PBMCs, which implies that BCL2-related complexes are enriched in AML cancer blasts." (PMID 39025942, 2024). "When we cocultured these APG-2575-treated cancer cells with genetic alteration of BCL-2 with IL-4-activated macrophages, we found that neither downregulation nor upregulation of BCL-2 in the cancer cells altered the expression of M1/M2-related markers." (PMID 38062129, 2024). "The outcomes showed that in the majority of cancer cases, LIPT2 expression was eminently positively correlated with MKI67, PCNA, BCL2, BAX, and EPCAM, while showing a significant negative correlation with VIM." (PMID 38129565, 2023). "The expression levels of Bcl-2 and Nrf2 did not increase through CAP treatment in the cancer cell lines." (PMID 37241912, 2023). "The feasibility of re-purposing specific MCL-1 and BCL-2 inhibitors to limit M.tb growth, using inhibitors that are in clinical trials and FDA-approved for cancer treatment has not be tested previously." (PMID 37864894, 2023). "Although the progression of several Bcl-2-ASO candidates through clinical trials has ended in failure, due to adverse effects and limited efficacy, the potential of this technology in cancer therapies has not been dispelled." (PMID 35056993, 2022). "Analysis of apoptosis-related genes, including BAX, BCL2, and CASP3 expression, suggested that the combination therapy did not have more effect in inducing apoptotic pathways in both cancer and normal cell lines in comparison with CAP or CUR alone." (PMID 34825002, 2021). "These proteins, which include BCL-2, BCL-XL, MCL-1, BCL-W and BFL-1, are key negative regulators of the intrinsic apoptosis pathway which is deregulated in most, if not all cancers." (PMID 34581776, 2021). "This point is especially critical since the same Bcl-2 proteins and BH3-containing interactors are not necessarily the fundamental ones to target for all the cancer types." (PMID 31825969, 2019). "This anti-correlation between MYC and BCL2 appears to be an exception rather than the rule since we primarily found a positive correlation between MYC and BCL2 expression in the pan-cancer CCLE cohort." (PMID 31375684, 2019). "Caspase-3, Bcl-2, Ki67, and VEGF expressions were not changed significantly in treated carcinoma cells." (PMID 30970626, 2019). "However, the occurrence of shifts in cytosolic [Ca2+] may not be a general phenomenon, as on-target Bcl-2 inhibitors, like ABT-737127 and venetoclax/ABT-199128, do not trigger these early cytosolic [Ca2+] elevations, even not in cancer cells that are dependent on Bcl-2 for their survival." (PMID 29491433, 2018). "We found that, despite not having representatives of their families, TLR7, BCL2, EZH2, and MDM2 for example, scored highly using the druggability models (74% or higher using the all-drug-target model; and 85% or higher using the cancer-drug-target model)." (PMID 26699810, 2015). "We found the selective upregulation of TRAIL and downregulation of BCL2, BIRC3 and PRKCE in the MDAMB-231 cancer cells but not in the MCF10A cells." (PMID 25950488, 2015). "All three of these Sp-regulated genes play a role in cancer cell growth and survival and some studies show that expression of survivin, EGFR and bcl-2 are negative prognostic factors for patients with RCC." (PMID 26035713, 2015).
cancer (continued). "However, attempts to target Bcl-2 therapeutically using antisense technology to inhibit protein translation have not significantly improved outcomes for cancer patients, although improved oligonucleotide design may potentially enhance the efficacy of this approach." (PMID 23229564, 2013). "This is likely an important finding as, like BCL-2, MCL1 does not induce proliferation but rather promotes cancer cell viability by blocking apoptosis." (PMID 21625473, 2011). "Not all of the cancer cell lines expressed the same STAT3 downstream targets but cyclin D1, Bcl-2, survivin, DNMT1 and TWIST1 were among the most common STAT3 downstream targets expressed and were inhibited by the STAT3 inhibitor, FLLL32." (PMID 20712901, 2010). "Nevertheless, when studying the KLT- induced the apoptosis of cancer cell(HL60), Li Y make use of RT-PCR to detect the the gene expression of bcl-2, there was no significant change in genetic transcription after 24 hours when using KLT at 10 ul/ml." (PMID 18718024, 2008). "Moreover, there was no significant change in the levels of ATM, BCL-2, and TP-53 genes, but there were BAX (≈0.8 fold) genes significantly up-regulated when compared the negative control in HT-29 cancer cell lines." (PMID 40872562, 2025). "Additionally, these findings align with previous RNA interference reports demonstrating that BCL-xL but not BCL-2 is necessary for the survival of senescent HUVECs and senescent DOX-treated cancer cells." (PMID 35805077, 2022). "Similarly, the depletion of HSP70 activates a tumor-specific death mechanism that is independent of caspases and bypasses BCL2, suggesting that HSP70 and HSP90 are potential targets to induce apoptosis of cancer cells." (PMID 34203709, 2021). "JMJD3 could be targeted in nonresistant cancer cells, and EZH2 in both nonresistant cancer cells and estrogen-resistant cancer cells, to limit BCL2 activation." (PMID 33478063, 2021). "Also, the expression of Bcl-2 protein as an anti-apoptotic parameter was evaluated in RCE-treated and non-treated cancer cells (control)." (PMID 33891003, 2021). "In this study, the authors show that MYC, but not MYCN or MYCL, represses BCL2, resulting in cells that are uniquely sensitive to apoptosis, and find that CHK1 and AURKA inhibitors may be useful for treating these cancers." (PMID 31375684, 2019). "The most effective Bcl-2 inhibitors ABT-737 and its analog ABT-263 target Bcl-2 and Bcl-xL; however, only weakly inhibited Mcl-1 thus are not effective against cancers with elevated Mcl-1 levels." (PMID 31404252, 2019). "Western blotting, qRT-PCR, and luciferase reporter assays using cancer cell lines (HeLa and A549) revealed that TH3 is able to repress the transcription of c-MYC at a protein level without affecting BCL2 expression, suggesting the preferential recognition and stabilization of the c-MYC G4 by TH3." (PMID 30682877, 2019). "Last but not least, Bcl-2/Bcl-xl inhibitors such as ABT-263 and ABT-737 have synergistic interaction with PPI in gastric cancer cells in both pH 7.4 and pH 6.5 conditions, which has a broad prospect in the field of cancer treatment." (PMID 29789637, 2018). "Our finding that hypertonicity enforced BCL-2 addiction (and thus primed) cancer cells might therefore not only be of clinical relevance for TRAIL-based, but also other apoptosis-inducing cancer treatments." (PMID 29706657, 2018).